NAMPT (nicotinamide phosphoribosyltransferase)
Diseases named in the same sentence as NAMPT in open-access papers (continued):
Sharing a sentence is not in itself a finding about the gene and the disease.
tumor (continued). "In addition to the NAMPT mutations that have been identified preclinically as mediators of acquired resistance to NAMPT inhibitors, recurrent NAMPT mutations have been rarely (< 1%) described in patient tumor samples across multiple types of malignancies." (PMID 40342733, 2025). "Additionally, NAMPT has been shown to be associated with dysregulation of the tumor immune microenvironment, including immune surveillance evasion, immunosuppression, and immune tolerance." (PMID 40463392, 2025). "Recent advances have provided a wealth of information to better understand the pathogenic role of NAMPT in regulating the proliferation, migration, survival, and drug resistance of tumor cells, as well as its influence on the immune status of the tumor microenvironment." (PMID 40775221, 2025). "We have shown that NAMPT‐deficient macrophages lose their polarization toward the M2‐like phenotype in vitro; we next examined whether NAMPT deficiency affects tumor progression through macrophage polarization in vivo." (PMID 38308188, 2024). "NAMPT/SIRT pathway also contributes a lot to NET-associated tumor angiogenesis, in which SIRT3 is capable of regulating endothelial cells, thereby stimulating the ROS generation and modulating the hypoxia-inducible factor, culminating in the preferment of angiogenesis." (PMID 39430756, 2024). "Thus, further studies are required to confirm the usefulness of a combined NAMPT inhibitor plus NA as a treatment for NAPRT-deficient neoplasms." (PMID 38396769, 2024). "To test whether NAMPT is involved in the polarization of TAMs caused by the interplay with tumor cells, we co‐cultured tumor cells with macrophages." (PMID 38308188, 2024). "This expression may by elevated by adipose-derived stem cell secretion and tumor-associated macrophages, with the supportive environment and intracellular NAMPT expression providing a malignant environment." (PMID 36830834, 2023). "The best candidate hit, FK866, was then validated at biochemical and molecular levels, so evidencing a novel role of this NAMPT inhibitor in promoting—through the production of reactive oxygen species—DNA damage and telomere loss, two events inducing tumor cell death." (PMID 37858982, 2023). "Therefore, the coadministration of NA and NAMPT inhibitors has been proposed as a new therapeutic strategy, but only in tumours deficient in NAPRT." (PMID 36078035, 2022). "However, compared with the direct function of NAMPT, this effect is weakened, and NAMPT is still a tumor-causing factor in general." (PMID 35906622, 2022). "Whether tumor cells depend more on NAMPT or NAPRT is associated with the normal tissue from which the tumor originates, which was mentioned in the previous paper." (PMID 35906622, 2022). "By binding this site, STAT1 can promote NAMPT expression in tumor-associated macrophages." (PMID 35515130, 2022). "Tumor cells which are deficient in de novo pathway enzyme NAPRT1 are addicted to NAMPT." (PMID 34187548, 2021). "For example, in tumors that are rendered insensitive to NAMPT inhibitors (by mutating the enzyme in such a way that it is unable to bind to these compounds), there is still an important effect of the inhibitors themselves in tumor-bearing mice." (PMID 32477131, 2020). "The most important advance in the field in recent years has been the determination that the intracellular and the extracellular forms of NAMPT are linked to inflammation, and may be directly connected to an effect on the tumor microenvironment." (PMID 32477131, 2020). "Therefore, glucose deprivation induces NAMPT, which protects tumor cells from cell death that is caused by glucose starvation-induced ROS stress." (PMID 32722390, 2020). "As these agents are commonly used to treat tumors that harbor PPM1D mutations (e.g., DIPG), they could be combined with NAMPT inhibitors to further enhance tumor-selective cytotoxicity." (PMID 31439867, 2019).
tumor (continued). "Furthermore, tumors with high NAMPT expression levels were associated with poor prognosis, independently of tumor stage." (PMID 29245920, 2017). "Because NAMPT is closely associated with tumor stage, we segregated patients by tumor grade to determine whether the effects of the enzyme on survival were stage-related or stage-independent." (PMID 29245920, 2017). "It was demonstrated that NAMPT is overexpressed in several types of tumors, including breast, colorectal, gastric, lung, prostate, and other carcinomas, and its expression appears to be associated with tumor progression." (PMID 25486521, 2014). "Therefore, NAMPT is closely associated with tumor development." (PMID 40486861, 2025). "Also, NAMPT has been found involved in tumor-associated angiogenesis." (PMID 32477131, 2020). "Given its role in NAD metabolism, inflammation, and tumor survival, NAMPT inhibition represents a promising therapeutic strategy." (PMID 40282553, 2025). "We observed that within CD8+ T cells, the expression of NAMPT showed an even stronger correlation with T cell anti-tumor functions, including cell activity, cytotoxic ability, and chemotactic capacity." (PMID 40846839, 2025). "In conclusion, CANA inhibited tumor growth and EMT by inducing cell cycle arrest in CCA cells and its anti-tumor effect was enhanced when combined with NAMPT inhibitors." (PMID 39940750, 2025). "To identify potential combinations for GBM, we examined the correlation between NAMPT mRNA expression and drug response in patient-derived tumor biopsies from TCGA." (PMID 40563807, 2025). "Lastly, the combination of NAMPT inhibitors and disulfiram was confirmed to have a significant anti-tumor effect and extend animal survival." (PMID 40280967, 2025). "This upregulation of NAMPT was found to play a critical role in creating an immunosuppressive tumor microenvironment." (PMID 40282553, 2025). "In this scenario, we previously identified Vacor as a tumor antimetabolite toxified to VAD via NAMPT and NMNAT2, and able to prompt rapid and complete NAD depletion." (PMID 40955574, 2025). "NAMPT also plays a significant role in tumor immune evasion, impacting immune cell functions and regulating anti-tumor immune responses." (PMID 40775221, 2025). "Reduced RICTOR expression resulted in elevated NAMPT expression and increased mitochondrial respiration, contributing to the intrinsic tolerance of drug-naïve tumor cells to BRAF/MEK inhibition and fostering a BRAF inhibitor-resistant phenotype." (PMID 40775221, 2025). "NAMPT overexpression has also been observed in patient-derived panNET tissue, suggesting its potential role in tumor pathogenesis." (PMID 40723227, 2025). "This implicates NAMPT involvement with increased NAD development, leading to TNBC-associated phenotype of tumor growth and treatment resistance." (PMID 41436543, 2025). "Sphere formation assays further confirmed that NAMPT knockdown led to a reduction in both the size and number of tumor spheres, indicative of diminished CSC-like properties." (PMID 40083697, 2025). "Recent studies have shown that NAMPT is overexpressed in PC cell-lines and patient tumor samples compared to healthy prostate tissue." (PMID 41516287, 2025). "Extracellular nicotinamide phosphoribosyltransferase (eNAMPT), a secreted form of the intracellular enzyme NAMPT, is produced by a variety of cell types, including tumor cells, immune cells, adipocytes, fibroblasts, and endothelial cells." (PMID 40083697, 2025). "We also found that the combination of NAMPT inhibitors and disulfiram exerted a robust synergistic anti-tumor effect that effectively inhibited cell proliferation in vitro and extended survival in vivo." (PMID 40280967, 2025).
tumor (continued). "In some settings, overexpression of NAMPT correlates with increased tumor aggressiveness and poorer prognosis." (PMID 40342733, 2025). "To enhance anti-tumor effects, delay drug resistance, and minimize side effects, we sought a drug that synergizes with NAMPT inhibitors." (PMID 40280967, 2025). "Additional studies identified that tumor-secreted nicotinamide phosphoribosyltransferase (NAMPT) reprograms CD10+ALPL + neutrophils in the TME through the NTRK1 pathway, maintaining their immature state and suppressing maturation/activation." (PMID 40342932, 2025). "By maintaining NAD + levels, NAMPT supports T cell proliferation and enhances the differentiation and activity of Th1 cells, fostering an environment conducive to strong anti-tumor immunity." (PMID 39950116, 2025). "Since human plasma contains NA, we next evaluated the effect of NA on the anti-tumor effect of the NAMPT inhibitor GNE-617 to understand NAD+ production kinetics in a more biologically relevant environment." (PMID 40280967, 2025). "Consistent with this association, NAMPT inhibition with Daporinad significantly inhibited GBM cell migration in wound-healing assays, supporting its potential to limit tumor invasiveness." (PMID 40563807, 2025). "Mechanistically, lactate accumulation in the tumor microenvironment partially contributes to the transcriptional repression of NAMPT in NK cells." (PMID 40775221, 2025). "By modulating NAD+ metabolism, NAMPT represents a promising therapeutic target, and its inhibition can effectively disrupt tumor cell metabolism and induce tumor regression." (PMID 40775221, 2025). "Elevated expression of the NAMPT enzyme and extracellular NAMPT has been found in the tumor tissues of HCC patients." (PMID 40722609, 2025). "To evaluate how the activation of the NAD+ salvage pathway affects tumor growth, we evaluated the cell viability of the NAMPT inhibitor FK866 in combination with CANA to suppress the NAMPT-NAD+-SIRT1 pathway." (PMID 39940750, 2025). "NAMPT affects tumor cell proliferation and differentiation by participating in the NAD+ salvage pathway." (PMID 40486861, 2025). "This chromosomal deletion causes the haploinsufficiency of several key tumor suppressors located on chromosome 7, such as EZH2, PMS2, HUS1, and NAMPT." (PMID 40981111, 2025). "They correlated this lower NAMPT expression with the reduced expression of CD36, NEAT1, PRDM1, and PTGS2; all genes associated with tumor-promoting activity and macrophage-driven immunosuppression." (PMID 40282553, 2025). "The combo of docetaxel and the NAMPT inhibitor daporinad was found to achieve greater anti-tumor efficacy than either monotherapy treatment in the heterogeneous cellular mixtures." (PMID 41516287, 2025). "Adoptive transfer of neutrophils with inhibited NAMPT or SIRT1 decreased tumor angiogenesis and growth in murine models." (PMID 40050933, 2025). "ATG-019, which inhibits both PAK4 and NAMPT, has shown improved efficacy in combination with anti-PD-1 therapy in murine tumor models compared to anti-PD-1 alone, representing a novel treatment strategy for advanced solid tumors and non-Hodgkin’s lymphoma." (PMID 39925807, 2025). "For CD14+ monocytes, the extracellular NAMPT contributes to tumor angiogenesis, decreased antitumor immunity, and resistance to ICBs50,51." (PMID 38600248, 2024). "This indicates that NAMPT inhibition reduces tumor outgrowth by limiting the population of immunosuppressive tumor‐promoting M2‐like TAMs in TME." (PMID 38308188, 2024). "Recent studies show that NAD+ biosynthesis through the so-called “Preiss-Handler (PH) pathway”, which utilizes nicotinate as a precursor, actively operates in many tumors and accounts for tumor resistance to NAMPT inhibitors." (PMID 38396769, 2024). "In both IDH-mutant and MYC-driven GBM, NAMPT inhibition using either FK866 or GMX1778 decreased the growth of tumours in vivo." (PMID 38893173, 2024).
tumor (continued). "Meanwhile, NAMPT inhibitor FK866 is capable of accelerating tumor cell death, concomitantly with reductions in NAMPT expression and the NAD+ level." (PMID 39408693, 2024). "NAMPT-mediated signaling plays a key role in tumor progression by modulating proliferation, cell plasticity, cytokine secretion, angiogenesis, metastasis, and in microenvironment modifications." (PMID 38254798, 2024). "Naged promotes the generation of NETs by activating the histone deacetylase SIRT1 through the tumor-secreted nicotinamide phosphoribosyltransferase (NAMPT), thereby driving tumor metastasis." (PMID 38817858, 2024). "Our data show that NAMPT‐deficient TAMs initiate a higher levels of effector T cells (CD44highCD72Llow), suggesting that inhibition of NAMPT improves anti‐tumor immunity by enhancing cytotoxic T cell function." (PMID 38308188, 2024). "Compared with control cells (LLC Vector), LLC OE NAMPT cells were more sensitive to LZFPN-90 and FK866, further indicating that LZFPN-90 affects tumor cell survival by targeting NAMPT." (PMID 38448544, 2024). "When NAMPT expression was further analyzed in two groups of TAMs in the tumor tissues, SPP1+TAMs showed a greater increase in NAMPT expression with respect to monocytes compared to C1QC+TAMs." (PMID 38308188, 2024). "This is also consistent in our TNBC patient samples where Fn14 and NAMPT-high TNBC tumour samples had higher NAD + /NADH and intracellular ATP levels compared to their matched normal samples." (PMID 38965263, 2024). "NAMPT mRNA expression in immune cell subpopulations of tumor tissues were comparable to those in adjacent normal tissues." (PMID 38308188, 2024). "To mimic this expression pattern, we constructed a tumor model in which mice were inoculated with LLC cells overexpressing both NAMPT and PD-L1." (PMID 38448544, 2024). "NAMPT expression in macrophage clusters was comparable to that of monocyte clusters in adjacent normal tissues, however tumor tissues showed significant NAMPT upregulation in TAM clusters compared to monocyte clusters." (PMID 38308188, 2024). "Taken together, our data suggest that NAMPT deficiency in macrophages drive M1‐like TAM polarization and provide anti‐tumor activity via potentiated cytotoxic T‐cell activity in TME." (PMID 38308188, 2024). "Inhibiting nicotinamide phosphoribosyl transferase (NAMPT) to block NAD+ synthesis can inhibit tumour growth and has been carried out in clinical trials." (PMID 39090116, 2024). "Specifically, a smart prodrug is designed by conjugating “drugtamer” to a nicotinamide phosphoribosyltransferase (NAMPT) PROTAC using a tumor microenvironment responsible linker." (PMID 38639391, 2024). "NAD+ is highly important for anti-tumor immune functions and NAMPT is an important regulator of NAD+ availability." (PMID 37842241, 2023). "HNSCC tumor cells with NAMPT downregulation showed greatly reduced tumorigenic capabilities in vitro and in vivo." (PMID 36864434, 2023). "We observed that coadministration of the NAMPT inhibitor with the NAPRT inhibitor cooperated inhibiting tumor growth." (PMID 36864434, 2023). "The limited sample size makes it difficult to predict the modulatory effect of NAMPT, and further studies should enlarge the sample size to predict the effects of NAMPT and stemness-related genes on tumor size with a mathematical model." (PMID 36830834, 2023). "NAD+-depleting medications, such as NAMPT inhibitors, are therefore likely to be unsuccessful when used alone due to low tumor selectivity." (PMID 36899911, 2023). "The combination of NAMPT and CtBP inhibitors also cooperatively modulated CtBP's coregulatory activities and effectively attenuated tumor growth in a mouse xenograft model." (PMID 37707363, 2023). "Further studies are needed to shed light on the role of NAMPT in establishing the immunosuppressive tumor microenvironment." (PMID 38116009, 2023). "NAMPT-mediated glycolytic processes are also required for antitumor immunity of tumor-infiltrating macrophages." (PMID 37165408, 2023).
tumor (continued). "Nicotinamide phosphoribosyltransferase (NAMPT) also contributes a lot in TANs relevant tumor angiogenesis." (PMID 37679744, 2023). "Several studies have reported that c-MYC increased the expression and activity of SIRT1 mediated via transcriptional activation of NAMPT to drive tumor cell proliferation and progression." (PMID 38116009, 2023). "To further validate on-target functional inhibition of CtBP oncogenic activities by the 4-Cl-HIPP/GMX1778 combination relevant to tumor progression, we studied how combined CtBP/NAMPT inhibition impacts PDAC cell migration using a modified wound-healing assay." (PMID 37707363, 2023). "NAMPT has a function in tumor cell survival and growth and is upregulated in a number of solid tumors." (PMID 36899911, 2023). "As expected, we confirmed that the overexpression of NAMPT reversed the inhibition of tumor growth by NAM after high-dose NMN treatment, whereas NAM-restored cells combined with NAMPT inhibitor FK866 subsequently re-slowed the growth of tumors." (PMID 37173894, 2023). "NAMPT inhibition reduces tumor growth in vivo and combines with cisplatin and docetaxel in antitumor effects." (PMID 36864434, 2023). "Among them, three (NAMPT, PCDHA4, and AXL) have been reported to be associated with the pathogenesis of this tumor." (PMID 36918772, 2023). "In this work, we described the plasticity of different CSC subpopulations in HNSCC tumor cell lines, with NAMPT being a common marker increased in all of them." (PMID 36864434, 2023). "Inhibiting NAMPT in tumor cells reduces levels of intracellular NAD+ and extracellular adenosine, thereby enhancing CD8+ T cell functions." (PMID 37842241, 2023). "NAMPT is clearly important for cell homeostasis, and we have identified a novel IFNγ-induced mechanism by which NAMPT enhances tumor burden." (PMID 36900204, 2023). "Numerous tumor cells have been shown to increase the expression of nicotinamide phosphoribosyltransferase (NAMPT), which is essential for NAD+ salvage." (PMID 37046703, 2023). "Three of thirty-nine proteins (PCDHA4, AXL, and NAMPT) correlate with RMS and RMS-associated tumor behavior." (PMID 36918772, 2023). "Of note, being telomeres hardly reparable DNA regions, the accumulation of dysfunctions in these chromosomal sites would account—together with the metabolic activity of NAMPT inhibition—for the tumor cell death induced by drug exposure." (PMID 37858982, 2023). "Mechanistically, NAD+ deficiency in TILs drives mitochondrial dysfunction and reduces ATP production, whereas supplementation with nicotinamide (NAM), the substrate of NAMPT, reverses these effects to promote a strong anti-tumor immune response in vivo." (PMID 37842241, 2023). "Nevertheless, the apparent increased dependence of tumor cells on NAMPT activity still makes this enzyme an attractive target to explore." (PMID 36899911, 2023). "Single-cell RNA sequencing (scRNA-seq) showed a positive correlation (R = 0.097, P = 1.2e–05) between the expressions of NFIB and NAMPT in epithelium-derived tumor cells of CRC." (PMID 37491379, 2023). "It has been shown that CLL cells promote NLC differentiation in the tumor microenvironment by releasing soluble factors such as nicotinamide phosphoribosyl transferase (NAMPT) and the nuclear protein high-mobility group protein B1 (HMGB1)." (PMID 37958334, 2023). "The targeting of NAD + biosynthetic pathways with the inhibitors of nicotinamide phosphoribosyltransferase (NAMPT) or nicotinate phosphoribosyltransferase (NAPRT) showed anti-tumor effects and exerted sensitization to docetaxel in xenograft mice." (PMID 37453969, 2023). "In several mouse xenograft models, NAMPT inhibitors induced the inhibitory effect on tumor initiation and progression, leading to the prolongation of overall survival of the animals." (PMID 36765744, 2023).